IL1B (interleukin 1 beta)
Diseases named in the same sentence as IL1B in open-access papers (continued):
Sharing a sentence is not in itself a finding about the gene and the disease.
breast cancer (continued). "The primary aim of this study was to investigate the effects of blocking IL-1B activity through inhibition of the IL-1R, on breast cancer bone metastasis." (PMID 27765923, 2016). "IL-1β induced IL-6 production in breast cancer cells in a TG2-dependent manner, and other cytokines and growth factors including TGF-β, TNF-α, and EGF potentiated the effect of IL-1β on IL-6 expression." (PMID 27609180, 2016). "In mouse models, IL-1B and its receptor (IL-1R1) are upregulated in breast cancer cells that metastasise to bone compared with cells that do not." (PMID 27765923, 2016). "MCF7_TG2 cells showed increased invasiveness compared to MCF7_Cont cells, and IL-1β treatment further increased the invasiveness of MCF7_TG2 breast cancer cells." (PMID 27609180, 2016). "Here, our results demonstrate that the inflammasome and IL-1β pathway promoted tumor growth and metastasis in animal and human breast cancer models." (PMID 27786298, 2016). "MCF7_TG2 breast cancer cells grew more rapidly and formed a large spheroid in the 3D matrigel compared to MCF7_Cont cells, and IL-1β treatment further increased growth and conferred invasiveness and budding-like phenomena in MCF7_TG2 cells." (PMID 27609180, 2016). "Within the inflammatory tumor microenvironment, IL-1β increases luminal-type breast cancer cell aggressiveness by stimulating IL-6 production through a TG2-dependent mechanism." (PMID 27609180, 2016). "A 3D matrigel on top assay also revealed the synergistic effects of TG2 overexpression and IL-1β treatment on the invasion of MCF7 breast cancer cells." (PMID 27609180, 2016). "IL-1β induced IL-6 production from TG2-overexpressing MCF7 breast cancer cells in an NF-kB-, PI3K-, and JNK-dependent manner." (PMID 27609180, 2016). "Recent reports show that curdlan can inhibit TH2‐cell responses, promoting breast cancer progression 43; it was also reported to suppress IL‐5, IL‐13 and surprisingly IL‐1β from lymph nodes during epicutaneous sensitization." (PMID 26573878, 2016). "Our results show that inflammasome and IL-1β enhance tumor growth and metastasis in breast cancer models." (PMID 27786298, 2016). "The results show that IL-1β induced expression of IL-6 in breast cancer cells, and that TG2 overexpressing cells expressed over twenty times more than control cells after IL-1β treatment." (PMID 27609180, 2016). "When tumor and lung tissues were homogenized and analyzed by ELISA, mature IL-1β levels in primary mammary tumors and metastasis sites in MMTV-PyMT mice were significantly elevated." (PMID 27786298, 2016). "We then treated 293 cells with IL-1β for different times, and treated breast cancer MCF7 cells with IGF-1 for 1h." (PMID 26318844, 2015). "We have recently reported that IL-1β regulates the migratory potential of MDAMB231 breast cancer cells in normoxic conditions." (PMID 26696754, 2015). "Collectively, our findings underline the role of HIF-1α and NFκB in the complexity of migration program of MDAMB231 breast cancer cells in the presence of IL-1β under hypoxic conditions." (PMID 26696754, 2015). "In line with this, IL-1β expression is elevated in several human tumors (including breast cancer); thus, patients with high IL-1β levels have generally bad clinical outcome." (PMID 26327350, 2015). "We recently reported that TNF-α and IL-1β were minimally expressed by normal breast epithelial cells, but were highly expressed in tumor cells of biopsies from most breast cancer patients." (PMID 25928089, 2015). "Increased IL-1β also leads to mammary tumor growth and metastasis in part through inducing regulation of myeloid derived suppressor cells (MDSCs), which promote an immunosuppressive environment." (PMID 26106384, 2015). "Given the relevance of the interplay between inflammation and hypoxia in tumor progression, in this study we decided to investigate the role of HIF-1α and NFκB in MDAMB231 breast cancer cell migration under hypoxic conditions and in the presence of IL-1β." (PMID 26696754, 2015).
breast cancer (continued). "Our data suggest that aggressive breast cancer cells secrete IL-1β, which increases the production of chemokines by MSCs." (PMID 26362269, 2015). "It increases expression of IL-1β in human monocytes and in breast cancer cell lines, MCF-7 and ZR-75-1." (PMID 25511260, 2014). "While there is no direct evidence showing the involvement of inflammasomes in breast cancer, it has been reported that IL-1β plays a role in tumorigenesis and progression of breast cancer." (PMID 24474192, 2014). "Previous datasets from microarray experiments support our findings as they reveal a favourable outcome for ovarian and breast cancer patients who express high levels of IL1B." (PMID 23867201, 2013). "In line with previous reports from human monocytes, leptin induced IL-1β and IL-1Ra expression in breast cancer cells, which was related to the phosphorylation of mTOR/4E-BP1." (PMID 24202338, 2013). "Notably, we have shown that the expression levels of IL-1β in the primary tumours of breast cancer patients were significantly associated with their brain metastatic statuses, suggesting that IL-1β may serve as a potential prognostic marker and a therapeutic target for brain metastasis." (PMID 23495140, 2013). "In the case of mammary cancer, high levels of IL-1β have also been correlated with aggressive tumors and a high recurrence in patients." (PMID 22655200, 2012). "Interleukin 1β (IL-1β) is known to be present in mammary tumors, and its higher expression in the tumor microenvironment suggests its possible role in metastasis." (PMID 22655200, 2012). "The E-selectin ligand activity of the bone metastatic ZR-75-1 breast carcinoma cell line was tested by perfusing the breast cancer cells over IL-1β activated HUVECs under physiological flow conditions in the parallel plate flow chamber adhesion assay." (PMID 22970241, 2012). "In this study, we have identified the relationships between inflammatory chemokines and cytokines in breast cancer along different stages of disease, and have analyzed the potential roles of TNFα and IL-1β in promoting breast cancer progression." (PMID 21486440, 2011). "The inflammatory chemokines CCL2 (MCP-1) & CCL5 (RANTES) and the inflammatory cytokines TNFα & IL-1β were shown to contribute to breast cancer development and metastasis." (PMID 21486440, 2011). "In this study, we asked if associations exist between the inflammatory chemokines CCL2 & CCL5 and the inflammatory cytokines TNFα & IL-1β in breast cancer." (PMID 21486440, 2011). "To determine if this indeed the case, we have initiated this study by determining the expression patterns of CCL2, CCL5, TNFα and IL-1β in biopsy sections of healthy individuals and in breast cancer patients at different progression stages of disease." (PMID 21486440, 2011). "IL-1β is regulated by IL-1RA and activates estrogen receptors, which increase the proliferation of breast cancer cells." (PMID 20181040, 2010). "Studies of IL-1β in breast cancer have demonstrated that IL-1β expression is increased in 90% of oestrogen receptor-negative invasive breast carcinomas, and that it is localised to both tumour cells and stromal cells." (PMID 19393083, 2009). "Previous studies have demonstrated that treatment of breast cancer cells in culture with IL-1β promotes cell proliferation and migration." (PMID 19393083, 2009). "For example, treatment of breast cancer cells with IL-1β has been reported to activate the NFκB pathway and induce both cell migration and proliferation." (PMID 19393083, 2009). "In vitro studies of breast cancer cells have demonstrated the ability of IL-1β to promote proliferation and migration." (PMID 19393083, 2009). "We studied the influence of four common gene polymorphisms (IL1A -889C/T, IL1B -511C/T, IL1B +3953E1/E2, and IL1RN long/2) of the IL-1 family on survival in 262 Caucasian patients with breast cancer by univariate and multivariate survival analysis." (PMID 19267917, 2009).
breast cancer (continued). "IL1β levels are high in breast cancer tissue and correlate with invasiveness and an aggressive phenotype." (PMID 16842617, 2006). "The aim of this study was to evaluate any role of specific SNPs in the interleukin genes IL1A, IL1B, IL1RN, IL4R, IL6 and IL10 in predisposition to breast cancer susceptibility and severity." (PMID 16842617, 2006). "Neuroinflammatory and systemic inflammatory responses, particularly increases in pro-inflammatory cytokines (IL-6, IL-1β, TNF-α) and reductions in hippocampal BDNF, are consistently linked to breast cancer and chemotherapy-induced cognitive impairment in animal models." (PMID 41155372, 2025). "Moreover, in breast cancer cells exhibiting high sensitivity to IL-1β, stimulation with IL-1β markedly induces the upregulation of BIRC3 expression, consequently conferring resistance to doxorubicin treatment." (PMID 41035952, 2025). "Importantly, neutralization of IL-1β prevented breast cancer progression in a humanized mouse model." (PMID 40873585, 2025). "Furthermore, IL-1β has been detected in co-cultures of human breast cancer cells and monocytes, favoring in vitro invasion and aggressiveness." (PMID 39858071, 2025). "The success of canakinumab, another IL-1β-targeting agent, in reducing lung cancer incidence among patients with cardiovascular disease suggests that IL-1β blockade may possess broad oncologic utility extending beyond breast cancer." (PMID 41007766, 2025). "Therefore, the pharmacological inhibition of IL-1β represents a promising therapeutic strategy worthy of further investigation in breast cancer management." (PMID 40697377, 2025). "Consistently, pre-clinical models of breast cancer showed that blockade of IL-1β secreted by macrophages in the TME resulted in the accumulation of tumor-infiltrating dendritic cells and the tumor-infiltrating CD8+ T cells, promoting tumor regression over time." (PMID 39858071, 2025). "In summary, IL-1β is a critical mediator of inflammation-driven breast cancer progression." (PMID 41007766, 2025). "Additionally, IL-1β stimulation promotes nuclear translocation of β-catenin and increases the transcription activities of β-catenin target genes in breast cancer via EMT induction." (PMID 39858071, 2025). "IFN-γ and IL-1β both boosted the expression of PIGR in breast cancer cells." (PMID 40584290, 2025). "In breast cancer, IL-1β is often produced by activated macrophages and dendritic cells in the tumor microenvironment, and it can also be secreted by highly aggressive breast cancer cells, particularly in triple-negative breast cancer, which exhibits aberrant inflammasome activation." (PMID 41007766, 2025). "IL-1β selectively induced TSLP secretion from breast cancer cells." (PMID 40873585, 2025). "There are some genetic association studies conducted on Bangladeshi Breast cancer and cervical cancer population to evaluate susceptible single nucleotide polymorphisms of INSIG2, HLA-DRB1, GCNT1P5, IL1β, IL4R, IL6, FGFR2, CYP1A1, ESR1 genes and disease outcome." (PMID 40920780, 2025). "In breast cancer bone metastasis, IL-1β from tumor cells and the microenvironment can inhibit primary tumor growth by impairing the infiltration of innate immune cells with potential anti-cancer functions, while simultaneously promoting enhanced tumor cell migration and osteolytic metastases." (PMID 39125732, 2024). "In breast cancer, HIF-1α and the G protein-coupled estrogen receptor (GPER) signaling pathway stimulate the expression of VEGF in CAFs, while GPER in breast cancer CAFs induces interleukin-1β (IL-1β) to express interleukin-1 receptor 1 (IL1R1) in breast cancer cells." (PMID 39192979, 2024). "In this review, we first discuss the molecular mechanisms by which IL-1B drives the metastatic cascade of breast cancer bone metastasis before exploring potential methods for targeting IL-1 signalling that may benefit patients in the future." (PMID 38800348, 2024).
breast cancer (continued). "The production of IL-1β by the cancer cell also led to a more pro-tumor microenvironment, and its expression has been suggested to accelerate tumor growth, including many breast cancer cases." (PMID 38254674, 2024). "Notably, the mechanism by which IL1B regulates IL-8—a critical gene that mediates breast cancer invasion and metastasis to the lungs —and the role of AHR in such mechanism, is worth pursuing." (PMID 38982523, 2024). "Similarly, in breast cancer metastasis, BMAT secrete many factors including IL-1β and leptin which were shown to enhance migratory phenotype of breast cancer cells." (PMID 38625510, 2024). "Given their critical roles in immune regulation, tumor growth, metastasis, and bone remodeling, interleukins, such as IL-6, IL-8, IL-1β, and IL-11, have been useful in predicting the clinical stage and prognosis of patients with breast cancer which has metastasized to the bone." (PMID 39125732, 2024). "In addition, inhibition of IL-1 signaling with the anti-IL1β antibody or the IL1R antagonist inhibits bone metastasis in pre-clinical models of breast cancer." (PMID 39190284, 2024). "Additionally, invasion is directly proportional to IL-8 expression in several breast cancer cell lines and its expression in breast cancer appears to be induced by other cytokines (IL-1β, TNFα and IL-6), an/or hormones (progesterone and estrogen)." (PMID 37979099, 2024). "Treatment of breast cancer cells with TNF-α alone stimulated the release of IL-1B and IL-10." (PMID 39334821, 2024). "We searched PubMed and Google Scholar to find articles published in the last 10 years or so, using keywords including NLRP3, inflammasome, immune response, IL-1β, IL-18, pyroptosis, melanoma, leukemia, breast cancer, colon cancer, lung cancer, and other cancer types." (PMID 39769450, 2024). "While studies have suggested the pivotal function of NLRP3 and IL-1β in breast cancer development, we next investigated whether Sch B can inhibit the activation of NLRP3 inflammasome in TNBC cells." (PMID 38254674, 2024). "However, both IL-1β and TNF-α exhibit paradoxical pro-tumor effects that are associated with metastasis in breast cancer." (PMID 39474419, 2024). "Using GSDMD-deficient mice, we found that growth of implanted breast cancer, known to be dependent on IL-1β, as well as of hepatoma tumors was independent of the expression of GSDMD in the tumor microenvironment." (PMID 39224600, 2024). "Interestingly, lipid-accumulating lung mesenchymal cells promote the metastasis of breast cancer cells by metabolic rewiring of cancer cells and natural killer cells, partially via the IL-1β-HILPDA-ATGL axis." (PMID 38736892, 2024). "Furthermore, studies have shown that the BRCA1 mutation stimulates inflammasome activation and IL-1β secretion via ROS production and cGAS-STING activation, thereby promoting breast cancer metastasis." (PMID 38473997, 2024). "This review focuses on the mechanisms by which IL-1B promotes breast cancer bone metastasis." (PMID 38800348, 2024). "Targeting IL-1B signalling may be an effective way to prevent occurrence of breast cancer metastasis." (PMID 38800348, 2024). "The secretion of IL-8 and IL-1β by TAMs could further enhance the aggressiveness of EGFR+ HER2+ breast cancer." (PMID 36674955, 2023). "When the breast cancer cell lines were stimulated with proinflammatory cytokines both mRNA and secretion of total fibronectin were enhanced, especially with IL-1β." (PMID 36922898, 2023). "In contrast, a recent study found that IL-1β may hinder breast cancer metastasis by inhibiting the production of proliferative E-cadherin-positive progeny derived from metastasis-initiating cancer cells." (PMID 38066523, 2023). "Additionally, inflammasome pathway and IL-1β production can also be elicited by ATP or TNF-α through the P2Y2 receptor (P2Y2R) in breast cancer cells, which promotes the expression of matrix metallopeptidase-9 (MMP-9) and resultant invasion." (PMID 36932407, 2023).
breast cancer (continued). "Indeed, the mRNA expression levels of CXCL2, TGFB1, CCL2, and IL1B were markedly increased in the breast cancer cell lines after treatment with Doxo and Abe." (PMID 37993606, 2023). "IL-1β promotes breast cancer progression by increasing adipocyte VEGF secretion and angiogenesis." (PMID 36670988, 2023). "The NLRP3 inflammasome-dependent release of IL-1β induces the expression and release of immune cells, CD4 + T cells, and IL-22, which has been linked to the initiation and progression of many types of cancer, including breast cancer." (PMID 37715239, 2023). "In addition, we neutralized secreted IL-1β in the astrocyte-conditioned media before adding it to breast cancer cells." (PMID 37749707, 2023). "In a triple-negative breast cancer model IL-1β decreased the viability of breast cancer cell, further supporting that systemic IL-1β inhibition might contribute to cancer progression." (PMID 36611037, 2023). "Additionally, we aimed to evaluate the expression level of IL-1β, as a gene that plays a role in cell proliferation, in human breast cancer cells." (PMID 37700002, 2023). "Another source of CXCL1 in breast tumors may be adipose-derived mesenchymal stem cells (MSC), which increase CXCL1 expression under the influence of interleukin-1β (IL-1β) from breast cancer cells." (PMID 37108425, 2023). "In the current study, we convert to evaluate the differential expression and clinicopathological features of NLRP3 inflammasome pathway-related proteins, including NLRP3, caspase-1, ASC, IL-1β, and IL-18, in the tumor parenchymal and immune-stromal cells of breast cancer." (PMID 38031068, 2023). "Furthermore, in a spontaneous in vivo model of breast cancer, cancer cells stimulate systemic inflammation by producing IL-1β, which leads to stimulation of IL-17 production by γδT cells and can inhibit anti-tumor CD8+ T cell activity." (PMID 36835413, 2023). "Similarly, neutralization of IL-1β almost completely prevented increased proliferation of breast cancer cells coming in contact with the culture media of astrocytes." (PMID 37749707, 2023). "IL-1β has been reported to control tumor invasion, up-regulate the initiation and development of primary tumor, increase the aggressivity of luminal breast cancer cells, and increase IL-6 production through NF-κB pathway leading to tumor growth and aggressiveness." (PMID 36835413, 2023). "Besides, an increased serum IL-18 level was observed in the advanced-stage of breast cancer patients as well, which was consistent with IL-1β." (PMID 36823153, 2023). "According to several studies, raised levels of cytokine-mediated acute phase C-reactive protein, and pro-inflammatory cytokines, including IL-6, IL-1β, and TNF- α are found in breast cancer patients, documenting that breast cancer is associated with inflammation." (PMID 36978815, 2023). "Growth in the expression of IL1B was even more pronounced, being elevated almost tenfold in astrocytes exposed to the conditioned medium of parental breast cancer cells and approximately 30-fold in astrocytes cultured in the presence of factors secreted by brain metastatic cells." (PMID 37749707, 2023). "TAMs promote metastasis and invasion in breast cancer through the secretion of IL-1β." (PMID 37340387, 2023). "In detail, β-hydroxybutyrate secreted from adipocytes increases histone H3K9 acetylation and induces IL-1β and lipocalin 2 (LCN2) expression to enhance tumorigenicity in MCT2-expressing breast cancer cells, which in turn is linked to poor prognosis in breast cancer patients." (PMID 36670988, 2023). "Indeed, administration of IL-1β to the cell cultures was able to promote proliferation of both human and mouse breast cancer cells." (PMID 37749707, 2023). "The NLRC4/IL-1β signaling pathway has been shown to promote the progression of breast cancer." (PMID 37020871, 2023). "Factors derived from breast cancer cells, such as IL-1β, may drive bone metastasis by remodeling the bone microenvironment." (PMID 38041134, 2023).